NIPAL3 (NIPA like domain containing 3)
Synonyms: NPAL3; DJ462O23.2; SLC57A5
Tractability: Antibody: UniProt predicts a signal peptide or a membrane-spanning region.
Gene: Protein-coding gene on chromosome 1 (24,413,527 to 24,476,735, forward strand). Ensembl gene ENSG00000001461.
Subcellular location: Membrane
Subcellular location (Human Protein Atlas): Nucleoplasm
Pathways (Reactome):
Transport of small molecules: Miscellaneous transport and binding events
Gene Ontology:
Molecular function: protein binding; magnesium ion transmembrane transporter activity
Biological process: magnesium ion transport; magnesium ion transmembrane transport
Cellular component: membrane
Genetic constraint (gnomAD): Loss-of-function variants: 33 observed, 40.39 expected, observed/expected ratio (o/e) 0.82, 90% interval 0.62 to 1.09. The upper end of that interval is the gene's LOEUF score, 1.09, which puts it in group 4 of 6, group 1 being the genes least tolerant of losing a copy. Missense variants: 410 observed, 502.78 expected, observed/expected ratio (o/e) 0.82, 90% interval 0.75 to 0.88. Synonymous variants: 184 observed, 209.2 expected, observed/expected ratio (o/e) 0.88, 90% interval 0.78 to 0.99.
Homologues: Orthologues: macaque NIPAL3 (98% identical), pig NIPAL3 (95% identical), chimpanzee NIPAL3 (94% identical), dog NIPAL3 (94% identical), guinea pig NIPAL3 (92% identical), mouse Nipal3 (90% identical), rabbit NIPAL3 (89% identical), rat Nipal3 (80% identical), tropical clawed frog nipal3 (66% identical), zebrafish nipal3 (58% identical), Drosophila melanogaster spict (22% identical), Caenorhabditis elegans nipa-1 (20% identical). Paralogues in human: NIPAL2 (42% identical), NIPAL1 (22% identical), NIPA2 (21% identical), NIPAL4 (21% identical), NIPA1 (18% identical).
Diseases named in the same sentence as NIPAL3 in open-access papers:
NIPAL3 is named in the same sentence as 3 diseases in open-access papers, as found by Europe PMC text mining. Sharing a sentence is not in itself a finding about the gene and the disease. The quoted sentences say what the papers report.
keloid (1 paper, 2022). An irregularly shaped, elevated mark on the skin caused by deposits of excessive amounts of collagen during wound healing. "Using qPCR, three genes (SNED1, NIPAL3, and VTN) among 14 candidate genes were shown to be significantly changed by HOXA11-AS-knockdown keloid fibroblasts compared with normal keloid fibroblasts." (PMID 35432479, 2022). "Three genes, including SNED1, NIPAL3, and VTN, were validated by real-time PCR in HOXA11-AS-knockdown keloid fibroblasts." (PMID 35432479, 2022). "We obtained three PCR-validated genes (NIPAL3, SNED1, and VNT) without any detectable proteins by western blotting, even in normal keloid fibroblasts without HOXA11-AS knockdown." (PMID 35432479, 2022). "However, no detectable expression of SNED1, NIPAL3, and VTN was shown in either normal or HOXA11-AS-knockdown keloid fibroblasts using western blotting (data not shown)." (PMID 35432479, 2022).
cancer (1 paper, 2018). A tumor composed of atypical neoplastic, often pleomorphic cells that invade other tissues. "Five of the pan-cancer ALFRED genes (BRCA1, ATM, BRCA2, NSD1, and TPCN2) were individually significantly enriched for RDGVs in cases versus controls (P < 0.05 by pan-cancer case-control analysis) with one additional gene, NIPAL3, marginally significant (P = 0.07 by case-control analysis)." (PMID 29973584, 2018).
NIPAL3 also shares sentences with these, for which no sentence is quoted: major depressive disorder (1 paper).